AGR2 (anterior gradient 2, protein disulphide isomerase family member)
Diseases named in the same sentence as AGR2 in open-access papers (continued):
Sharing a sentence is not in itself a finding about the gene and the disease.
tumor (continued). "This latter result is consistent with previous findings from our laboratory demonstrating an enhancer switch in the AGR2 gene in this tamoxifen-resistant tumor model, thereby reducing the dependence of AGR2 expression on ER activity." (PMID 31562570, 2020). "The LINC00460 / miR-342-3p / AGR2 axis exerts anti-tumor effect in HCC in vitro and in vivo, consolidating and expanding the research about targeted gene therapy for early diagnosis and treatment of HCC." (PMID 32493835, 2020). "Our previous data demonstrated the anti-tumor property of H-1-2, which specifically inhibited AGR2 expression." (PMID 32322663, 2020). "The overexpression of AGR2 and its pro-oncogenic features indicate that AGR2 is a clinically-relevant anti-tumour target, hence researchers have begun developing antibodies against AGR2." (PMID 33005802, 2020). "AGR2 promotes tumour development and metastasis and its elevated expression is almost completely restricted to malignant tumours." (PMID 33005802, 2020). "Expression of CENPF, AGR2, and GDF15 was found to be enriched in mpMRI-visible tumours and was associated with reduced time to biochemical recurrence in an independent dataset, suggesting a potential link between mpMRI visibility and prognostic outcome." (PMID 33000006, 2020). "Conversely, silencing of ZEB1 led not only to increased levels of AGR2 protein, but also attenuated the invasiveness of tumor cells." (PMID 32570918, 2020). "Extracellular AGR2 secreted by cancer cells creates a concentration gradient for the nearby cells in the tumour microenvironment." (PMID 31710263, 2019). "AGR2 is one of the latent tumor angiogenesis factors, which has been mostly related to tumor cell proliferation, transformation, migration and drug resistance." (PMID 31475143, 2019). "Very few functions of extracellular AGR2 have been reported explaining the fibroblasts coordinated tumour cell invasion and promotion of angiogenesis." (PMID 31710263, 2019). "Altogether, our results suggest that, as soon as NIH3T3 fibroblast receives signal of AGR2, cells get activated and begin to elongate for migration and proliferation for the linear cellular organization which is believed to promote tumour growth." (PMID 31710263, 2019). "Due to frequent expression in common solid tumors, expression in premalignant lesions, circulating tumor cells and metastases, AGR2 represents an exciting cancer-specific target." (PMID 31303962, 2019). "AGR2 promotes cell migration, proposed as a potential drug target, and biomarker for circulating tumour cell detection." (PMID 31710263, 2019). "Anterior gradient-2 (AGR2), a tumor secretory protein is believed to play a pivotal role during tumor microenvironment (TME) development." (PMID 31710263, 2019). "This was evident even on relatively small tumor foci, suggesting that AGR2 is activated early following JSRV infection." (PMID 31434729, 2019). "The tumour-related function of intracellular and secretory AGR2 has been investigated intensively in promoting angiogenesis and fibroblasts modulation in TME formation." (PMID 31710263, 2019). "Functional AGR2 is effective only around the AGR2-secreting cells where tumour-secreted proteins in tumour interstitial fluid have different concentration magnitudes." (PMID 31710263, 2019). "Recombinant human endostatin is an anti-angiogenic agent used for tumor treatment that has been coupled to AuNPs to reduce cell migration and tube formation in vitro (HUVECs), induced by anterior gradient 2 (AGR2)." (PMID 31475143, 2019). "Based on previous studies, we assert that AGR2 secreted by tumour cells create a gradient in TME believed to regulate stromal cells like fibroblasts." (PMID 31710263, 2019). "AGR2, a member of the protein disulfide isomerase family, is also a proto-oncogene, and the extracellular form of AGR2 has been seen to induce tumor metastasis in various in vivo animal models." (PMID 31906196, 2019).
tumor (continued). "Differentially expressed genes (DEGs) between these high (mRNA expression z-score levels of AGR2 > 1.5) and low (z-score < -1.5) AGR2 expression tumor groups from the METABRIC study were identified using the cutoff of BH q-value < 0.05." (PMID 29796176, 2018). "Two genes identified in HG3 tumor epithelial cells are broadly implicated in many cancers with worse prognoses, PIGR and AGR2." (PMID 30383866, 2018). "AGR2 expression occurred more often in patients with lower GS (42% in patients with GS <7 when analysing percentage of tumour cells, and 52.3% when cytoplasm was analysed)." (PMID 30559929, 2018). "Increased tumor AGR2 mRNA expression was associated with decreased DSS among 1,341 women (per each standard deviation increase of AGR2 expression: HR 1.14, 95% CI: 1.01-1.29, P = 0.03)." (PMID 29796176, 2018). "Altered AGR2 RNA expression levels with the tumour grade and stage, similar to our IHC data were also observed in the TCGA data." (PMID 30140383, 2018). "Evidence exists from other tumours that cells with upregulated AGR2 acquire a metastatic, proliferative and invasive phenotype." (PMID 30140383, 2018). "The functional role of increasing AGR2 in promotion oncogenesis has been established by the activation of survival pathways and metastasis, but little is known about how the reduction in AGR2 would act facilitating tumor progression." (PMID 29845750, 2018). "An association between the Gleason score (GS) and the percentage of positive tumour cells and intensity of AGR2 was found (p=0.017, and p=0.032, respectively)." (PMID 30559929, 2018). "Pooled analyses revealed that AGR2 overexpression had an unfavourable impact on OS (HR 1.93, 95% CI 1.32–2.81) and time to tumour progression (TTP) (DFS/RFS/PFS) (HR 1.60 95% CI 1.06–2.40) in solid tumour patients." (PMID 29138453, 2017). "Both FOXM1 and AGR2 induce tumor growth, progression, invasiveness and maintain mucinous characteristics in PIMAs." (PMID 29267283, 2017). "In normal goblet cells, AGR2 is required for folding and processing of secreted (MUC5AC) and membranous mucins (MUC1, MUC2, MUC5B;) which have also been implicated in various tumor-promoting processes." (PMID 29267283, 2017). "In summary, our study sheds new light on PDAC initiation and development and reveals the induction of the pro-oncogenic AGR2 protein in pancreas before manifested neoplasia." (PMID 27941872, 2017). "In recent years, the role of AGR2 in tumor development and progression is becoming more and more intensively studied." (PMID 28810836, 2017). "The validation of TGF-β as a potent suppressor of AGR2 expression in our panel of tumor cell lines is consistent with the previous findings that have characterised AGR2 as a TGF-β responsive gene." (PMID 28810836, 2017). "In digestive cancers, the expression of cathepsins is up-regulated by tumor-promoting factors, such as C-myc, K-ras, AGR2, MAPK, p38, and the Hh signaling pathways." (PMID 28402938, 2017). "Consistent with important role of FOXM1 and AGR2 in PIMAs, inactivation of either AGR2 or FOXM1 was sufficient to inhibit the tumor growth, invasion and metastasis in orthotopic mouse model." (PMID 29267283, 2017). "Levels of AGR2 in PDAC inversely correlate with the extent of epithelial-to-mesenchymal transformation (EMT) of the tumor." (PMID 29069604, 2017).
tumor (continued). "While tumor promoting genes such as AGR2 were downregulated, known tumor suppressor genes like NDRG2 and DAPK1 were upregulated 4.3- and 4.6-fold, respectively." (PMID 28231808, 2017). "In the present study, we identified AGR2 as an important factor contributing to the maintenance of the epithelial phenotype of tumor cells." (PMID 28810836, 2017). "A549 scramble and A549 cells with AGR2 knockout were analyzed by a colony scattering assay measuring the ability of epithelial tumor cells to detach from colonies in culture, mimicking some aspects of tumor invasiveness." (PMID 28810836, 2017). "Our sensitive targeted SRM assays should also facilitate biomarker analysis of other cancers, especially for markers like secreted AGR2 that are widely present in many tumor types." (PMID 29254211, 2017). "It has already been described for various cancer progression-associated factors such as AGR2, SIP1 and YB1 to promote on the one hand tumor cell migration while inhibiting tumor growth on the other hand as demonstrated for NMU in our SKBR3 in vitro model." (PMID 28423716, 2017). "To further document the biological function of eAGR2, we have used different human adenocarcinoma organoids genetically depleted for AGR2 and showed the decreased ability of cancer cells to form tumor organoids." (PMID 27240165, 2016). "Remarkably, the addition of recombinant human AGR2 (40 ng/ml) to the medium of AGR2-depleted tumor cell lines reversed the cell growth inhibition induced by AGR2 depletion." (PMID 27240165, 2016). "In contrast, AGR2 overexpression in non-tumor organoids (HBEC-AGR2) forced the secretion of eAGR2 (~30% in the extracellular medium)." (PMID 27240165, 2016). "In 129/152 evaluable spots of tissue taken from the centers of primary tumors, 24% showed AGR2 immunostaining, whereas in 124/152 evaluable spots taken from the tumor invasion fronts, 12% showed AGR2 immunostaining." (PMID 26894971, 2016). "Remarkably, the addition of the human recombinant AGR2-ΔKTEL (40 ng/ml) to the extracellular medium of AGR2-depleted organoids was still able to restore the formation of tumor organoids." (PMID 27240165, 2016). "Other reports have documented the pro-oncogenic activity of AGR2 in various types of cancer, supported by in vivo experiments showing increased tumour growth and metastasis derived from AGR2-expressing cells." (PMID 27025787, 2016). "AGR2 was a major common molecule in the media of LuCaP 70CR and 10-076 CP as indicated by strong immunostaining of the respective tumor tissue." (PMID 27283903, 2016). "This demonstrates the specific presence of ER-resident AGR2 in extracellular medium from non-tumor organoids overexpressing AGR2 (HBEC-AGR2)." (PMID 27240165, 2016). "To confirm that eAGR2 is indeed, an ECM microenvironmental pro-oncogenic protein, we investigated the effects of overexpressing AGR2 in human bronchial epithelial non-tumor cells." (PMID 27240165, 2016). "Although the iAGR2-mediated ER proteostasis control model is appealing, it was also observed that in cancer, AGR2 was present in the extracellular space, serum, and urine, thereby opening other avenues for its role on tumor microenvironment." (PMID 27240165, 2016). "The anterior gradient homolog 2 (AGR2) protein plays an important role in the proliferation and migration of tumor cells, and the detection of AGR2 is very useful in cancer diagnosis." (PMID 28660021, 2016). "To ensure that the presence of eAGR2 in the extracellular medium correlated to its overall level of expression, we also assessed the levels of eAGR2 in non-tumor organoids overexpressing AGR2 (HBEC-AGR2)." (PMID 27240165, 2016).
tumor (continued). "Immunohistochemistry of AGR2 in a cohort of 34 non-small cell lung cancer (NSCLC) patients revealed that AGR2 was overexpressed in tumors compared to adjacent non-tumor tissue." (PMID 27240165, 2016). "MAPK/ERK signaling was shown to regulate AGR2 expression in tumor cell lines in response to physiological stress from serum and oxygen depletion." (PMID 26445321, 2015). "Cell lines transfected with AGR2 produced metastasis in a xenograft model, showed gain of anchorage-independent growth and promoted tumor growth." (PMID 26445321, 2015). "The prevalence of AGR2 overexpression in several tumour types and its correlation with patient survival has engendered much interest in the use of AGR2 as a serum or urine biomarker for disease detection." (PMID 26169982, 2015). "We also noted a remarkable increase in AGR2 immunoreactivity in the original tumor of the pathological lymph node-positive patient (pN1, n = 20, P < 0.01) compared with the pathological lymph node-negative patient (pN0, n = 39)." (PMID 25871396, 2015). "For all tumor cores, the high AGR2 fractions were 59 % for grade 1, 48 % for grade 2, 43 % for grade 3, and 22 % for grade 4." (PMID 26445321, 2015). "The widespread expression of AGR2 in human cancer underscores its potential importance in tumor biology." (PMID 26445321, 2015). "For NSCLC in younger patients, higher tumor AGR2 expression is correlated with a poorer survival in our cohort." (PMID 26445321, 2015). "Tumor AGR2 expression was arbitrarily sorted into high with integrated intensity >1, and low with integrated intensity ≤1." (PMID 26445321, 2015). "AGR2 enhances several tumor-specific phenotypes including cell proliferation, survival, anchorage-independent growth, invasiveness through MatrigelTM and metastasis." (PMID 25367337, 2014). "The mechanism linking AGR2 to tumor invasion and metastasis is involved in several molecular alterations such as CTSB and CTSD." (PMID 24717913, 2014). "AGR2 is expressed in several human tumor tissues rich in epithelial cells, like prostate, breast, small intestine, colon, lung, and pancreas." (PMID 25237833, 2014). "We have now improved these studies to cover AGR2 transcript levels in urine extracellular membrane vesicles (exosomes) as these samples are usually enriched in tumor-specific transcripts." (PMID 25237833, 2014). "In this case, aberrant AGR2 expression in poorly differentiated cancer is correlated with worse prognosis of the patients, suggesting that tumor promoting role of AGR2 is specific to tumor type and stage." (PMID 25367337, 2014). "By analyzing AGR2 expression and its tumor-promoting role in vitro and in vivo, we have provided evidences for tumor-promoting activities of AGR2 in ampulla of Vater cancer cells for the first time." (PMID 25367337, 2014). "Despite that both SNU-478 and SNU-869 cells were originated from tumors of the ampulla of Vater, they were different from each other in their AGR2 expression, differentiation status, growth kinetics and drug responses." (PMID 25367337, 2014). "AGR2 is also positively correlated with in vivo tumor-forming ability in athymic nude mice and metastasis of tumor cells." (PMID 25367337, 2014). "Results of the present study clearly suggest that down-regulation of integrins, mediated by low AGR-2 levels, is initially required for the detachment of the tumor cells from the basement membrane and for the breaking of cell-cell contacts." (PMID 24587138, 2014). "Invasion of the tumor cells was significantly increased by AGR2 overexpression in the SNU-869:AGR2 cells." (PMID 25367337, 2014). "The results indicated significantly reduced (p<0.01) tumor cell migration in AGR-2-silenced PC3 cells when compared to control PC3 cells." (PMID 24587138, 2014). "The observed failure of the SNU-478:KD2 cells to form tumor clearly supports a tumor-promoting role of AGR2 expression in vivo." (PMID 25367337, 2014).
tumor (continued). "Tumor tissue samples from patients with unfavorable PFS status were found to overexpress four out of the five genes (AGR2, ALDH6A1, TFF2, MCM5) and underexpress KLF12." (PMID 24555920, 2014). "AGR2 was also significantly increased in PDAC compared to the benign disease group and PDAC compared to the other cancer group (p = 2.11E-06 and p = 4.54E-10, respectively)." (PMID 24007603, 2013). "AGR2 is a protein shown to promote tumor growth, cell transformation and migration; however it is unclear as to why AGR2 was able to distinguish other cancers from PDAC in this study." (PMID 24007603, 2013). "In this situation, relatively lower levels of AGR2 expression predicted a higher likelihood of tumor recurrence." (PMID 21144054, 2010). "Recent evidence suggests that AGR2 can promote tumor growth, promote cancer cell survival, cell migration, and cellular transformation." (PMID 20550709, 2010). "The involvement of both MDK and AGR2 in oncogenesis and tumor progression has been previously reported." (PMID 20525245, 2010). "The HR for survival of patients with AGR2-positive tumours compared to AGR2-negative tumours was 3.0 (95% CI 1.3–6.9)." (PMID 16598187, 2006). "The presence of immunocytochemical staining for AGR2 was cross-tabulated with the established prognostic factors of tumour size, nodal status, histological grade, lymphovascular invasion, ERα and PgR status." (PMID 16598187, 2006). "The percentage of positive carcinoma cells in tumours directly correlates with the level of AGR2 mRNA (Spearman's rank correlation, P=0.0007) and protein (linear regression analysis r2=0.95, P=0.0002)." (PMID 16598187, 2006). "Transforming growth factor-β1 (TGF-β1) produced by CRC cells promotes the migration of peripheral blood neutrophils (PBNs), giving PBNs characteristics similar to TANs, which further promotes the secretion of AGR2, forming a positive feedback loop and exacerbating tumor progression." (PMID 40510589, 2025). "Furthermore, a study identified a crosstalk between tumor-associated neutrophils (TANs) and CRC cells through the AGR2-CD98hc-xCT axis, which enhances CRC cell migration and creates a feedback loop driving metastasis." (PMID 40160822, 2025). "Moreover, we identified a positive correlation between AGR2 overexpression and tumor grade, TNM stage and LNM stage." (PMID 41239615, 2025). "ETV has been shown to suppress AGR2 expression, a protein that promotes tumor growth and migration." (PMID 41011271, 2025). "Additionally, the expressions of MACC1 and AGR2 were positively correlated, with their overexpression collaboratively driving tumor cell proliferation, invasion, metastasis, and EMT." (PMID 41239615, 2025). "Consequently, our findings imply that KAI1, MACC1, and AGR2 should be regarded as valuable biomarkers for this malignancy, particularly in the context of predicting tumor metastasis and patient outcomes." (PMID 41239615, 2025). "Additionally, among patients with tumor sizes <4.0 cm, 15 out of 48 (15/48, 31.3%) exhibited positive AGR2 expression, compared to 24 out of 58 (24/58, 41.4%) in those with tumors measuring 4.0 cm or greater." (PMID 41239615, 2025). "Furthermore, we used the information generated in transcriptional studies in natural and experimental OPA, and we employed immunohistochemistry to detect the levels of AGR2 (the most relevant upregulated gene) in tumor cells." (PMID 40941427, 2025). "AGR2 (anterior gradient 2) is a protein disulfide isomerase family member and is involved with endoplasmic reticulum homeostasis, cellular proliferation, and tumor progression." (PMID 41200187, 2025). "AGR2, FXYD3, TFF1, and MUC13 are associated with increased tumor grade." (PMID 39682235, 2024).